RAD51 (RAD51 recombinase)
Diseases named in the same sentence as RAD51 in open-access papers (continued):
Sharing a sentence is not in itself a finding about the gene and the disease.
breast cancer (continued). "In search of a novel and rational therapeutic combination for TNBC, several studies identified RAD51 as target in synthetic lethal screens for PARP inhibition in breast cancer." (PMID 27507046, 2016). "Breast cancer 2 (BRCA2) facilitates the replacement of RPA with RAD51, and the resultant RAD51-ssDNA filament searches for a homologous DNA sequence on the identical sister chromatid." (PMID 26983989, 2016). "RAD51 plays a central role in DNA repair by forming a complex with BRCA2, but its overexpression in breast cancer has been found to be associated with poor prognosis." (PMID 27959953, 2016). "In breast cancer, several lines of evidence have implicated overexpression of EZH2 and repression of tumor suppressors such as KRT5, KRT6, CDH3, RAD51 paralogs, CDKN1C, FOXC1, Wnt/β-catenin signaling (c-Myc, Cyclin D1, Axin2), RKIP and KLF2." (PMID 27835578, 2016). "In light of the hyper-recombination phenotype induced by RAD51 G151D presented in this study, we suggest that RAD51 G151D contributed to the refractory and aggressive nature of the breast cancer from which it was identified." (PMID 27513445, 2016). "The knockdown of CtIP in breast cancer MCF7 cells reduced Rad51 foci numbers and enhanced f H2AX foci formation after f-irradiation, suggesting that deficiency of CtIP decreases homologous recombination repair and delays DNA double strand break repair." (PMID 26713604, 2016). "Taken together, it is unlikely that RAD51, XRCC3, and XRCC2 have a significant contribution to breast cancer susceptibility." (PMID 25918678, 2015). "To evaluate the contribution of RAD51, XRCC3, and XRCC2 mutations to breast cancer predisposition, we screened 182 familial Finnish breast or ovarian cancer patients for germline variation in the RAD51 and XRCC3 genes and 342 patients for the XRCC2 gene." (PMID 25918678, 2015). "The association of RAD51, XRCC3, and XRCC2 haplotypes with breast cancer risk was studied among 1516 breast cancer cases (including 592 familial cases) and 1234 population controls." (PMID 25918678, 2015). "We undertook a meta-analysis on RAD51 135G > C data for 21236 cases and 19407 controls pooled from 28 studies on breast cancer in women." (PMID 26108708, 2015). "Breast cancer (BRC) motifs of human BRCA-2 are involved in the interaction with human RAD51 (HsRAD51), and are reported to inhibit the filament formation of HsRad51." (PMID 26111183, 2015). "In the literature, many reports confirm the significance RAD51 gene polymorphisms in the 5′UTR, regarding the risk of breast carcinoma." (PMID 25743260, 2015). "Increased spontaneous RAD51 nuclear foci were observed in cell lines derived from a wide variety of cancers including acute myeloid leukemia, T-cell lymphoma, breast carcinoma and melanoma." (PMID 25765654, 2015). "Using breast tissues TMA, we confirmed that high level of RAD51 correlates with advanced histological grading in breast cancer, consistent with a previous report.." (PMID 24811120, 2014). "In this study, we used human breast cancer cells MDA-MB-231 to investigate the ability of B02 to inhibit RAD51 and to potentiate an anti-cancer effect of chemotherapeutic agents including doxorubicin, etoposide, topotecan, and cisplatin." (PMID 24971740, 2014). "Increased RAD51 expression has been correlated with poor clinical outcome in lung cancer, prostate cancer and in ER+ breast cancer." (PMID 24811120, 2014). "In breast cancer and also soft-tissue osteosarcoma cell lines, DOX arrests cells in S and G2, and induces RAD51 expression causing resistance to the drug." (PMID 25401086, 2014). "Germline mutations in BRCA and RAD51 genes, involved in DSB repair, are strongly associated with hereditary breast cancer." (PMID 25409685, 2014). "Consistent with previous work our observations demonstrate RAD51 is more highly expressed in aggressive breast cancer when compared to normal tissue." (PMID 24811120, 2014).
breast cancer (continued). "This analysis suggested that RAD51 expression is increased during breast cancer progression and metastasis and an oncogenic role for RAD51 when deregulated." (PMID 24811120, 2014). "(iii) Analysis of HR defects in sporadic human breast cancer patients showed low RAD51 scores being a strong predictive marker of pathologic complete response to chemotherapy." (PMID 24641873, 2014). "We confirm for the first time in breast cancer cells that RAD51 and c/EBPβ interact in situ and confirmed this by co-immunoprecipitation of endogenous proteins." (PMID 24811120, 2014). "We utilized in silico analysis of gene expression datasets, clinical pathology and cellular biology studies to show that one of the DNA repair genes RAD51 was over represented in high grade and metastatic breast carcinomas." (PMID 24811120, 2014). "In the present study, we found that SAHA enhanced DNA damage after IR through the inhibition of DNA repair proteins (including Rad51 and DNA-PK) in breast cancer cells." (PMID 24130769, 2013). "RAD51 was reported to have a significantly increased expression in immortalized and tumor cells, including breast cancer." (PMID 23977219, 2013). "Abnormally elevated RAD51 function and hyperactive homologous recombination (HR) rates have been found in a panel of cancers, including breast cancer and chronic myeloid leukaemia (CML)." (PMID 23341130, 2013). "In this study, we used clinical specimens and confirmed the role of XRCC3 and RAD51 in development and progress of breast cancer." (PMID 23977219, 2013). "Cancers, including acute lymphocytic leukaemia, acute/chronic myeloid leukaemia, pancreatic cancer, breast cancer, etc, depend on elevated RAD51 functions and enhanced HR rate for their proliferation, survival and drug resistance capabilities." (PMID 23341130, 2013). "Data showed that expressions for both XRCC3 and RAD51 were significantly increased in breast cancer." (PMID 23977219, 2013). "In this study, immunohistochemistry was used to explore the prevalence of XRCC3 and RAD51 expression and their possible roles in breast cancer." (PMID 23977219, 2013). "Our results showed that the expression levels of both XRCC3 and RAD51 were significantly increased in breast cancer, which was consistent with their high mRNA expressions." (PMID 23977219, 2013). "A total of 57 breast cancer patients who underwent SSPBI were genotyped for SNPs (single nucleotide polymorphisms) in XRCC1, XRCC3, GST and RAD51 by Pyrosequencing technology." (PMID 22272830, 2012). "In breast cancer cell lines with high level of Akt1 activity, IR-induced Brca1 and Rad51 foci formation and HRR are strongly impaired compared to cells with low Akt1 activity." (PMID 22481935, 2012). "The cytoplasmic retention of Brca1 and Rad51 also correlates with activated Akt1 in sporadic breast cancer tissues." (PMID 22481935, 2012). "Biopsies of sporadic breast cancer patients show strong correlation of Akt1 activation with cytoplasmic Brca1 and Rad51 localization." (PMID 22481935, 2012). "The breast cancer suppressor BRCA2 controls the recombinase RAD51 in the reactions that mediate homologous DNA recombination, an essential cellular process required for the error-free repair of DNA double-stranded breaks." (PMID 21789034, 2011). "Here, we explore the relationships between the MSA and the Rad51 gene, which encodes a DNA repair enzyme that interacts with BRCA1 and BRCA2, in BRCA1 mutation carriers and women with sporadic breast cancer." (PMID 21708019, 2011). "Some SNPs also showed a significant effect on survival outcomes, such as RAD51-135 G>C in breast cancer, XRCC2 R188H in pancreatic cancer, and SNPs of RAD51-135 G>C and XRCC3 T241M in acute myeloid leukemia." (PMID 21647442, 2011). "These in vitro findings correlated with elevated nuclear RAD51 and RPA staining of breast cancer tissue from a patient with the M1775R mutation." (PMID 21666281, 2011).
breast cancer (continued). "The human breast cancer suppressor protein BRCA2 controls the functions of the RAD51 recombinase, an enzyme conserved in all kingdoms of life, which carries out the strand exchange reaction central to homologous DNA recombination (HDR)." (PMID 21789034, 2011). "The assembly of RAD51 at DNA damage sites is regulated by a number of RAD51 cofactors, including the tumor-suppressor gene BRCA1 (Breast Cancer Susceptibility Gene 1), BRCA2, and five RAD51 paralogs (RAD51B/C/D and XRCC2/3)." (PMID 19180185, 2009). "Rad51 assembly is regulated by the breast cancer suppressor Brca2, via its evolutionarily conserved BRC repeats, and a distinct carboxy (C)-terminal motif whose biological function is uncertain." (PMID 19540122, 2009). "LG2 markers include 190 genes, among which are many oncogenes, (BCL2 (down, breast cancer poor prognosis marker), RAD51 (up), EGFR (up), RUNX3 (up), BCL9 (down) and VAV3 (down) and tumor suppressor gene NME1 (up)." (PMID 17683614, 2007). "Despite the presented evidence for a role for deregulated expression of RAD51 in DSB repair defects and/or breast cancer, there have been few studies assessing the effects of RAD51 gene variation on breast cancer risk." (PMID 16762046, 2006). "The inclusion criteria for a 'high-risk' family was similar to the current study, but we specifically investigated breast cancer patients and several families that shared a haplotype in the RAD51 region." (PMID 16762046, 2006). "There are numerous reports of RAD51 overexpression in a large range of cancer cell lines, including cervical cancer, prostate cancer and breast cancer." (PMID 16762046, 2006). "Increased levels of the kinase ataxia telangiectasia mutated (ATM), which mediate the HR pathway, were found in chemoresistant breast cancer cells, and cisplatin treatment was associated with increased expression of the DSB repair protein RAD51, inducing chemoresistance in breast cancer cells." (PMID 39863855, 2025). "Notably, aberrant expression of the BCKDK/p‐RNF8/RAD51 axis correlates with breast cancer progression and poor patient survival." (PMID 40298908, 2025). "For RAD51, the expression in all the breast cancer cell lines were similar to HEK293." (PMID 40764992, 2025). "Moreover, and in agreement with preceding data, loss of SETD1A also restored Olaparib-induced RAD51 foci formation and thus HR activity in both BRCA1-mutated ovarian and breast cancer cell lines and in ATM-mutated lung cancer cells." (PMID 39994444, 2025). "Therefore, we determined the functional HR status of 53 breast cancer (BC) and 38 ovarian cancer (OC) cell lines by measuring the formation of RAD51 foci after irradiation." (PMID 38398132, 2024). "Several studies have functionally assessed HR based on RAD51 expression, mostly in breast cancer." (PMID 38725623, 2024). "In the RADIOLA study, the RAD51-foci score is investigated if it has a predictive value on Olaparib efficacy in g/sBRCA or PALB2 or RAD51C/D mutation carrier advanced breast cancer patients; no results were posted." (PMID 38540206, 2024). "For example, RAD51 recombinase (RAD51) and Breast cancer type 1 (BRCA1), genes involved in double-stranded break homologous recombination, are linked to the development of ovarian and breast cancers and are also downregulated in uterine fibroids." (PMID 37107181, 2023). "The functional relationship between RECQ5 and RAD51 in breast cancer is further supported by the studies showing that the overexpression of RECQ5, particularly when combined with low RAD51 expression, has been associated with increased invasion and migration in breast cancer." (PMID 37626846, 2023). "In addition, FOXM1 regulates downstream proteins, including survivin, RAD51, which contribute to homologous recombination DNA repair in breast cancer cells and, cyclin B1, a cell cycle regulatory protein." (PMID 37242455, 2023).
breast cancer (continued). "Here, we demonstrate, for the first time, that SOC therapies used in ER+ breast cancer induce DNA damage, and toxic PARP1 trapping upon generation of a functional BRCAness phenotype through loss of key DNA repair proteins, including BRCA1, BRCA2 and RAD51." (PMID 37914699, 2023). "Therefore, oncogenic fusion tyrosine kinases inhibitors or RAD51 phosphorylation inhibitors can inhibit DDR of breast cancer cells and can be used in combination with chemotherapy drugs to enhance the sensitivity of breast cancer cells." (PMID 35311116, 2022). "However, mutations in other HRR genes, such as ATM, CHEK2, PALB2, NBN, MRE11, and RAD51 paralogs RAD51C and RAD51D also increase cancer risk and are already included in many screening panels for breast cancer." (PMID 36139526, 2022). "Consistently, RAD51 overexpression in breast cancer cells increased DNA breaks." (PMID 36428789, 2022). "As for HR, there are few inhibitors that directly target HR proteins, but cytokines that indirectly regulate HR, such as RAD51 inhibitors, may also be candidate targets for breast cancer treatment." (PMID 35311116, 2022). "RAD51 overexpression, a key protein of homologous recombination, is also linked to overall poor survival and endocrine resistance in breast cancer, although the exact underlying signaling pathways are not well understood yet." (PMID 35401937, 2022). "In this study, we analyzed the expression levels of RAD51, a DNA homologous recombination repair-related molecule, in canine mammary tumor cell lines derived from the primary tumor CHMp and metastatic tumor CHMm, which were established from the same individual." (PMID 36548864, 2022). "In particular, a link between the expression of BRCA1 and RAD51 and the development of mammary tumors was hypothesized in dogs." (PMID 36288156, 2022). "A small molecule which binds specifically to DNA helicase RECQL5 and stabilizes the interaction between RECQL5 and RAD51 could inhibit the proliferation of breast cancer cells in a RECQL5-dependent manner." (PMID 35855837, 2022). "we looked for a role for HspBP1 in Rad51 foci formation in response to IR in breast cancer cells." (PMID 35387978, 2022). "In conclusion, the current study showed that CCNE2, CDCA5, RAD51, TCF19, KNTC1, MCM10, and NEIL3 might contribute to EPT-related tumorigenesis in breast cancer, with CCNE2 might be a sensitive risk indicator of breast cancer risk in women using MHT." (PMID 36233194, 2022). "However, evidence also suggests that RAD51 expression is increased during breast cancer progression, and overexpression of RAD51 in colorectal cancer was a predictor of poor outcome." (PMID 35626165, 2022). "Further therapeutic targeting of RAD51 in BRCA1 L1780P mutant breast cancer is warranted." (PMID 35626017, 2022). "The breast cancer CSCs have the BMI1 protein placed around stalled replication forks to engage RAD51 to activate the homologous recombination machinery to confirm that the BMI1/RAD51 axis is necessary to prevent cisplatin-induced cisplatin DNA damage." (PMID 36550571, 2022). "The data suggested that Rad51 was involved in the oncogenic process and may serve as a significant marker and target of breast cancer in tumor therapy." (PMID 33842359, 2021). "Similarly, RAD51 was downregulated in breast cancer cell line MDA-MB-231 upon HMGA1 depletion (GSE35525)." (PMID 34716319, 2021). "In a cohort of 23 breast cancer patients without a gBRCA mutation but with high suspected hereditary breast cancer, less than 10% RAD51 foci were detected in 14 of 23 tumors." (PMID 33670893, 2021). "measures RAD51 foci in proliferating cells from fresh breast cancer tissue after ex vivo radiation." (PMID 34722237, 2021). "The RAD51 gene is a pivotal homologous recombination gene and has already been found to be overexpressed in the following tumors: cervical cancer, non-small cell lung cancer, breast cancer, ovarian cancers, pancreatic cancer, melanoma and glioblastoma." (PMID 33148191, 2020).
breast cancer (continued). "Meanwhile, the RAD51 score could more predictively discriminate PARPi sensitivity between PARPi resistance in breast cancer PDXs than the conventional genomic test." (PMID 32005272, 2020). "Indeed, it was demonstrated that RAD51 is a functional biomarker that enables the identification of PARP inhibitors-sensitive breast cancer cases." (PMID 33240314, 2020). "Additionally, decreased RAD51 expression has also been observed in certain cancers, particularly sporadic breast cancers." (PMID 33015624, 2020). "However, other researchers have indicated that BRD4 inhibition decreases RAD51 expression and homologous recombination repair, thus potentially inducing DNA damage in prostate and breast cancer cells." (PMID 32208449, 2020). "Among those, CHEK1 is a checkpoint kinase that is essential for normal and cancer cells, GATA3 is a critical transcription factor with known oncogenic role, and RAD51 has been reported as an oncogene with elevated expression in multiple cancer types including breast cancer." (PMID 31980032, 2020). "Additionally, the presence of RAD51 foci in germline BRCA-proficient breast cancers correlates with resistance to PARPi." (PMID 33015624, 2020). "Since epidemiological and other population-based studies indicate existence of racial disparities in different ethnic populations for breast cancer in breast cancer progression and therapy, we further analyzed the expression of RAD51 between different races and their survival probability." (PMID 31492187, 2019). "Interestingly, there was a discrepancy in RAD51 expression in racial groups, with African-American and Asian breast cancer patients showing elevated RAD51 expression compared to Caucasian breast cancer patients." (PMID 31492187, 2019). "Interestingly, RAD51 levels can be used as an indicator of the efficacy of PARPi treatments in breast cancer." (PMID 31775907, 2019). "Moreover, compared with MKI67, RAD51 was found to be a better indicator to distinguish AI-resistant breast cancer from all AI-treated breast cancer in neoadjuvant settings." (PMID 31506496, 2019). "All these results supported RAD51 as a potential prognostic and therapeutic target of breast cancer, which could promote further fine stratification approach for AI-resistant population with ER-positive breast cancer." (PMID 31506496, 2019). "Therefore, all those results suggested that the overexpression of RAD51 was involved in breast carcinogenesis, resistance to AI and had unfavorable impacts on the overall survival of patients affected by breast cancer." (PMID 31506496, 2019). "It suggested that aberrant hypermethylation of BRCA2 was associated with its downregulation of expression but also with an overexpression of RAD51, which may lead to AI-resistance and poor prognosis in breast cancer." (PMID 31506496, 2019). "In addition, MAPK12 is associated with breast cancer, while XRCC2 is part of BCDX2 complex, which acts downstream of BRCA2 recruitment and upstream of RAD51 recruitment." (PMID 31870274, 2019). "Additionally, RAD51 expression levels were much higher in African-American and Asian breast cancer patients compared to Caucasians, suggesting RAD51 as a biomarker for racial disparities in breast cancer." (PMID 31492187, 2019). "All above results demonstrated that the methylation of BRCA2 led to its diminished expression, which caused incomplete suppression of RAD51 thus elevating the expression of RAD51, and hence an unfavorable outcome of breast cancer, especially ER-positive breast cancer." (PMID 31506496, 2019). "Besides, a decreased expression of RAD51 was found in low-methylated BRCA2 breast cancer samples (P = 0.022)." (PMID 31506496, 2019). "BRCA1 and RAD51 are classical proteins involved in double-strand break repair through homologous recombination and both proteins have high clinical relevance for breast cancer." (PMID 30939818, 2019).